CST3 (cystatin C)
Diseases named in the same sentence as CST3 in open-access papers (continued):
Sharing a sentence is not in itself a finding about the gene and the disease.
tumor (67 papers, 2004 to 2026). "Among these abnormal laboratory parameters, neutrophils, LDH, UA, and cystatin-C are all linked to the inflammatory microenvironment, which can significantly impact tumor development and progression." (PMID 31167668, 2019). "In contrast, cystatin C overexpression was associated with decreased glioblastoma cell invasion in vitro and tumor growth in vivo." (PMID 21085595, 2010). "In addition, osteopontin (OPN) and IGFBP-4 have been linked to chemoresistance, survival prediction, and tumor progression, whereas cystatin C has gained attention for its role in regulating protease activity and promoting metastasis." (PMID 41149076, 2025). "This might contribute to the hypothesis that in the presence of increased tumor mass or high cell turnover and associated increased cystatin C, the use of the eGFRcys equation leads to an underestimation of renal function." (PMID 36143104, 2022). "Finally, mutations in the CST3 gene within tumor cells may lead to the production of unstable cystatin C monomers, promoting oligomerization." (PMID 41233352, 2025). "Cystatin C: Cystatin C is a low-molecular-weight protein primarily known for its role as an endogenous inhibitor of cysteine proteases (cathepsins), which are crucial in tumor invasion and metastasis." (PMID 41438588, 2026). "Stefin B and cystatin C, intracellular and extracellular protease inhibitors, respectively, can modulate tumor biology through protease-dependent and protease-independent mechanisms." (PMID 41744803, 2026). "To investigate the role of cystatin C in human tumor development, we established a humanized mouse model by transplanting human cord blood-derived CD34+ cells into NSG-SGM3 mice." (PMID 41233352, 2025). "Among the DEGs, we detected some marker genes (CD74, RAB11FIP1, and CST3) related to tumor invasion which are highly expressed in region C3." (PMID 40639417, 2025). "The tumor-suppressive role of cystatin C is attributed primarily to its ability to inhibit cysteine cathepsins—enzymes that promote invasion by degrading extracellular matrix (ECM) proteins and processing various growth factors and cytokines." (PMID 41233352, 2025). "Here, we establish a direct link between oligomeric cystatin C—a cysteine cathepsin inhibitor and a well-characterized amyloidogenic protein—within the tumor microenvironment and the immune inhibitory receptors LILRB2 and LILRB5 on myeloid cells." (PMID 41233352, 2025). "Depletion of cystatin-C adversely affects tumorcell proliferation, leading to reduced tumor growth in an orthotopicmouse model of BC." (PMID 41181894, 2025). "Given that both myeloid and tumor cells are major sources of cystatin C within the TME, prolonged exposure to an acidic environment likely contributes to its oligomerization." (PMID 41233352, 2025). "CST3 silencing disrupts these immunosuppressive effects, leading to enhanced T-cell cytotoxicity and suppressed tumor growth in vivo." (PMID 41233352, 2025). "Engagement of these inhibitory receptors by oligomeric cystatin C enhances the immunosuppressive activity of myeloid cells, leading to T-cell suppression and tumor progression." (PMID 41233352, 2025). "TMX4, ALPL, PTX3, BHLHE40, TNFRSF12A and CST3 demonstrated significant overexpression in LUSC tumour tissues, whereas CLDN1, VKORC1 and ADD3 exhibited significant underexpression in the HPA database." (PMID 38520221, 2024). "In this investigation, we unveiled a new mechanism underlying the tumor-promoting effect of MC-LR in TME and highlight the potential of targeting the MC-LR/M2-TAM/TGF-β1/CST3 axis as a therapeutic strategy for CRC." (PMID 37445705, 2023). "Older age, larger tumor size, lower preoperative eGFR, higher serum cystatin C, and shorter TFS were correlated with worse short-term eGFR." (PMID 37906264, 2023). "Creatinine/cystatin C ratio also can help pathological staging and tumor markers to stratify the prognosis of CRC patients in more detail." (PMID 37409249, 2023).
tumor (continued). "Their findings revealed that cystatin C expression levels in ccRCC tissues were lower than in surrounding non-tumor tissues (P < 0.001)." (PMID 36589819, 2022). "Patients with low cystatin C expression in tumor tissues had a longer OS than those with elevated cystatin C expression." (PMID 36589819, 2022). "The results showed that cystatin C levels were significantly higher in tumor tissues than in normal tissues, but the immunohistochemical expression of cystatin C in non-neuroendocrine prostate cancer cells gradually decreased with increasing Gleason grade." (PMID 36589819, 2022). "Serum creatinine and serum cystatin C levels differentially depend on muscle and tumor mass, respectively." (PMID 36143104, 2022). "Among pre-palliative care factors, sex, age, tumor stage, Karnofsky performance status, neutrophil count, hemoglobin, lactate dehydrogenase, albumin, uric acid, and cystatin-C were identified as independent prognostic factors for OS." (PMID 31167668, 2019). "To better understand the role of cystatin C in tumor cell proliferation at the molecular level, we next investigated the level of protease activity and the proliferation rate of the primary PyMT;CstC-/- and PyMT;CstC+/+ tumor cells." (PMID 29088746, 2017). "Our underlying assumption in the interpretation of this scoring of patients based on predicted cystatin C levels and tumor invasion involves patient presentation of symptoms." (PMID 26349896, 2015). "Recently, cystatin C was suggested as an independent prognostic factor for the survival in some tumours." (PMID 23986888, 2013). "Implanted CST1-GFP and CST3-GFP cells (4 weeks) each enhanced tumor growth relative to the control, and we confirmed the higher CST1 and CST3 expression in implanted tumor tissues." (PMID 24357805, 2013). "Cystatin C was shown to be secreted by different cell types, especially by activated macrophages, as well as by some tumor cells." (PMID 23984285, 2013). "Cystatin C and cystatin B, endogenous inhibitors of cysteine proteases, possibly were involved in tumour growth and cell proliferation." (PMID 23986888, 2013). "One approach to directly evaluate the effect of cystatin C on tumor initiation and evolution uses animal models with either increased or decreased expression of this inhibitor." (PMID 21085595, 2010). "Enhanced SCC formation in Cstc−/− K14-HPV16 transgenic mice compared with those wild-type for cystatin C suggests the importance of this endogenous cathepsin inhibitor in early tumor progression in vivo." (PMID 21085595, 2010). "Several studies have convincingly demonstrated that cystatin C is an important inhibitor of cathepsin B and tumor cell invasion." (PMID 19956729, 2009). "Cystatin C is believed to prevent tumor progression by inhibiting the activities of a family of lysosomal cysteine proteases." (PMID 19956729, 2009). "Using a TMA comprising benign and tumor samples from 448 patients, we showed an inverse correlation between cystatin C and MMP2 expression." (PMID 19956729, 2009). "Although we measured a decrease in lung tumor burden following tail vein injection in the cystatin C over-expressing clone, this clone still resulted in tumor colonization." (PMID 15904519, 2005). "The correlation between high levels of tumour cystatin C and the longer survival of our patients concurs with the concept of protective role of high levels of cysteine proteinase inhibitors in tissue homogenates." (PMID 15138478, 2004). "The median level of cystatin C in tumour tissue was 1.18 times lower than that in corresponding mucosa (P=0.031)." (PMID 15138478, 2004). "In univariate analysis, the patients with low tumour cystatin C levels exhibited poor disease-free survival (DFS, P=0.013) and disease-specific survival (DSS, P=0.013)." (PMID 15138478, 2004). "In our study it is noteworthy that cystatin C level in control samples of the group of cystatin C positive tumours was significantly lower than in the control group with decreased inhibitor." (PMID 15138478, 2004).
tumor (continued). "Immunohistochemical quantification of cystatin C expression suggested that the concentration of immunoreactive protein in the cells of some tumour types seems to be below the detection limit." (PMID 15138478, 2004). "A large body of literature has been accumulated to suggest that cystatin C participated not only in the transformation of cells to a malignant state but also in tumour growth, invasion and metastasis." (PMID 15138478, 2004). "While cathepsin B promotes extracellular matrix degradation, cystatin C may act as a compensatory response aimed at limiting tumor progression." (PMID 41149076, 2025). "In addition, CST3 expression was linked to favorable outcomes, whereas CTS7 expression was highly correlated with tumor immune infiltration." (PMID 40747123, 2025). "To determine whether this altered tumor growth was associated with changes in the TME, we performed immune profiling of tumor tissues from cystatin C−/− mice." (PMID 41233352, 2025). "The top three were cystatin C increased, tumor marker abnormal and pseudocirrhosis." (PMID 41259313, 2025). "Notably, TMX4, ALPL, PTX3, BHLHE40, TNFRSF12A and CST3 demonstrated significant overexpression in LUSC tumour tissues, whereas CLDN1, VKORC1 and ADD3 exhibited significant underexpression." (PMID 38520221, 2024). "Cystatin C exerts a series of complex effects that may result in either an inhibition or a promotion of tumour cell growth and dissemination, as demonstrated by previous research." (PMID 38263244, 2024). "As shown in this study, loss of functions of either CST3 or SNCG could curtail the budding of RTP cells and prevent tumor repopulation, which provide an attractive therapeutic opportunity for sensitizing radiotherapy." (PMID 36658726, 2023). "Cystatin C is almost exclusively glomerular filtration-dependent, but changes in its level are observed in neoplasms and during steroid therapy, which is one of the treatment methods for neoplasms, such as acute leukaemias." (PMID 35056416, 2022). "However, in this same model CST3−/− tumors were less aggressive, as they were less capable of metastasizing to the lungs, consistent with a tumor-suppressive role." (PMID 33172965, 2021). "Our previous TAILS-based study showed that cystatin C is a substrate of extracellular cath-D and is completely degraded by multiple cleavage, highlighting the complexity of the proteolytic cascades that operate in the tumor microenvironment." (PMID 33995652, 2021). "Cystatin C is an important inhibitor of cathepsin B and tumor cell invasion." (PMID 32180899, 2020). "Cystatin C is associated with the proteolytic cascade and MAPK/Erk pathway together with AR may act in a synchronized manner to promote tumor growth and invasion into surrounding tissues." (PMID 19956729, 2009). "This suggests that cystatin C may mediate tumor cell invasion by modulating the activity of MAPK/Erk cascades." (PMID 19956729, 2009). "In the present study, we explored whether cystatin C is related to AR in androgen-independent tumor cell invasion and metastasis." (PMID 19956729, 2009). "A slight decrease in subcutaneous tumor growth was noted for a cystatin C over-expression clone." (PMID 15904519, 2005). "In the present study, a significantly lower concentration of cystatin C was found in the total population of tumour homogenates compared to normal mucosa, although two groups of patients with downregulated and upregulated cystatin C concentration were distinguished." (PMID 15138478, 2004). "In our study, we observed inverse correlation between the tumour cystatin C level and more aggressive forms of the disease (i.e., involved neck nodes, extranodal tumour spread), which also links the alterations in cystatin C expression with the invasive behavior of SCCHN." (PMID 15138478, 2004).
tumor (continued). "The tumour cystatin C level correlated inversely with pN-stage (pN0vs pN+: 18.4 vs 14.2 ng mgp−1, P=0.047), whereas a trend of lower cystatin C levels was observed in the group with extranodal tumour extention compared to that with no extranodal spread (14.0 vs 17.4 ng mgp−1, P=0.069)." (PMID 15138478, 2004). "Therefore, the majority of clinical work has been related to cystatin C activity and protein level determination in fluids surrounding tumours, mainly in the blood and urine." (PMID 15138478, 2004). "Thus, the results of the study have been related to established clinical and histopathological features, considering especially the correlation of individual tumour levels of cystatin C with patients’ survival." (PMID 15138478, 2004). "Additionally, cytokine analysis of sorted splenic Mac1+Gr-1+ myeloid cells from tumor-bearing mice revealed that compared with WT controls, cystatin C deletion significantly increased the expression of proinflammatory cytokines, including TNF-α, IL-1β, and IL-12." (PMID 41233352, 2025). "Specifically, mast cells not only secrete mediators related to pro-tumor function such as trypsin-like enzymes, chymotrypsin, vascular endothelial cell growth factor and histamine, but also mediators related to anti-tumor progression such as cystatin C and IL-17F." (PMID 39814702, 2025). "The development of fully evolved in situ SCC in Cstc−/− mice, but not in Cstc+/+ mice, suggests that cystatin C deficiency may reduce tumor cell apoptosis and/or increase tumor cell proliferation." (PMID 21085595, 2010). "Further, cystatin C may mediate tumor cell invasion through MAPK/Erk2 signalling pathways." (PMID 19956729, 2009). "Additionally, higher total concentrations of cystatin C found in sera of patients with lung, colorectal and melanoma cancer suggested enhanced secretion of cystatin C from tumour cells, increasing at the same time the intracellular proteolytic potential of cysteine proteases." (PMID 15138478, 2004). "Cystatins, particularly CST3, inhibit these proteases, potentially reducing ECM breakdown and thus limiting tumor invasion." (PMID 40747123, 2025). "Simultaneously, oligomeric cystatin C binds to the inhibitory receptors LILRB2 and LILRB5 on myeloid cells, thereby increasing their immunosuppressive activity and contributing to tumor progression." (PMID 41233352, 2025). "Forced expression of human cystatin C significantly accelerated tumor growth in hCD34+ humanized mice but not in NSG-SGM3 mice, suggesting that the tumor-promoting effects of cystatin C depend on human immune cells." (PMID 41233352, 2025). "This study established a seven-gene profile (FGG, C3, FGA, JUN, CST3, CPSF4, and HIST1H2BH) prognostic stratification system demonstrated in LUSC based on Tumor Progression, Immune Infiltration, and Stem Index." (PMID 37841237, 2023). "CRISPR‐based knockout of CST3 or SNCG in HCT116 significantly suppressed the colony formation capacities, elevated tumor sensitivity to irradiation and inhibited the subcutaneous tumorigenicity in vivo." (PMID 36658726, 2023). "By performing immunohistochemistry of PDO155 and pathology specimens of this patient, we confirmed that CST3 and CHI3L1 proteins were heterogeneously expressed in PDO155 and even in the original tumor tissue." (PMID 36810117, 2023). "In vivo, the mice in the MC-LR/AOM/DSS group had more tumor nodules, deeper tumor invasion, and higher M2 macrophage infiltration compared to the AOM/DSS group, and the expression of TGF-β1 and CST3 in tumors was consistent with the cellular level." (PMID 37445705, 2023). "In the present study, there was a significant correlation between cystatin C with LDH, suggesting an underestimation of renal function in patients with high cell turnover or tumor mass." (PMID 36143104, 2022). "Our results are consistent with the tumor suppressive capacities of CST3, as CIRBP promotes clonogenicity and anchorage-independent growth by down-regulating CST3 levels." (PMID 33172965, 2021).
tumor (continued). "In multivariate analysis, the prognostic value of cystatin C was compared to the values of pN-stage, UICC pTNM-stage, extranodal tumour spread and the presence of tumour emboli in the lymphatic vessels." (PMID 15138478, 2004). "While tumor growth kinetics were similar between sgScramble and sgCST3 B16-F10 clones in WT mice, cystatin C−/− mice presented significantly reduced tumor growth and lower endpoint tumor weights for sgCST3, but not sgScramble, B16-F10 tumors." (PMID 41233352, 2025). "As expected, forced expression of human cystatin C in B16-F10 or CT-2A cells significantly accelerated tumor growth in LILRB2KI mice but not in WT mice." (PMID 41233352, 2025). "Upregulation of RTP gene markers (SNCG, CST3 and RPS12) was also found in three resected tumor samples we collected from pPR (pathological partial response) LARC patients after receiving nCRT, which was coherent with the poor regression grade of these patients." (PMID 36658726, 2023). "Creatinine/cystatin C ratio may be an effective prognostic marker for predicting PFS and OS in CRC patients, aid in pathological staging, and along with tumour markers help in-depth prognostic stratification in CRC patients." (PMID 37409249, 2023). "RT‐PCR detection of budding RTP gene‐expressions in PDX model post two times 8 Gy irradiation revealed that most RTP gene levels (CST3, CDC37, IGFBP6, ISYNA1, RN7SL2) increased on day 9 when RTP cells were significantly enriched and partial fell back on day 82 when tumor repopulated." (PMID 36658726, 2023). "Taken together, it is legible that MC-LR could promote the infiltration of M2 macrophages, elevate the expression of TGF-β1, and downregulate the expression of CST3 in vitro and vivo in CRC to exacerbate the progression of the tumor." (PMID 37445705, 2023). "Creatinine/cystatin C ratio may be an effective prognostic marker for predicting PFS and OS in CRC patients and can help pathological staging and tumor markers to perform more detailed prognostic stratification in CRC patients." (PMID 37409249, 2023). "They found very low amounts of CST3 mRNA in the samples and ruled out the possibility of using cystatin C as the specific tumor marker for RCC." (PMID 36589819, 2022). "Tumor parameters (tumor size, number of tumors, pathological features, all P>0.05) had no statistically significant changes in serum cystatin C levels." (PMID 36589819, 2022). "Taken together, the precise role for cystatin C in tumor progression is not fully elucidated and remains controversial." (PMID 29088746, 2017). "Taken together, these data suggest a role for cystatin C in tumor cell proliferation, but not in apoptotic cell death or angiogenesis, potentially explaining the significant reduction of PyMT tumors in CstC-deficient mice." (PMID 29088746, 2017). "The tumour cystatin C level correlated inversely with pN-stage (P=0.047), whereas a trend of lower cystatin C levels was observed in the group with extranodal tumour extension compared to those with no extranodal spread (P=0.069)." (PMID 15138478, 2004). "The sence-cystatin C transfected cells were also markedly less invasive than the control cells and, in nude mice, did not form tumours upon intracerebral injection." (PMID 15138478, 2004). "Furthermore, a cytokine array analysis showed increased Il33 and Cst3 expression in both tumor and serum from KPC-Cdh11+/+ mice compared to KPC-Cdh11+/- mice, while Il11 was highly enriched in KPC-Cdh11+/+ serum alone and Ccl11 was enriched in tumor alone." (PMID 37954069, 2023). "However, subsequent detailed statistical modelling indicated that CST3 did not add particular value in classifying CRC tumor stage." (PMID 31467500, 2019). "Absence of cystatin C also enhanced tumor tissue extract cathepsin activities." (PMID 21085595, 2010). "Thus, the elevated cystatin C levels observed in our malignant group may reflect this protease-inhibitor imbalance rather than being directly tumor suppressive." (PMID 41149076, 2025).